FOXP1 (forkhead box P1)
Description:
Transcriptional repressor. Can act with CTBP1 to synergistically repress transcription but CTPBP1 is not essential (By similarity). Plays an important role in the specification and differentiation of lung epithelium. Acts cooperatively with FOXP4 to regulate lung secretory epithelial cell fate and regeneration by restricting the goblet cell lineage program; the function may involve regulation of AGR2. Essential transcriptional regulator of B-cell development. Involved in regulation of cardiac muscle cell proliferation. Involved in the columnar organization of spinal motor neurons. Promotes the formation of the lateral motor neuron column (LMC) and the preganglionic motor column (PGC) and is required for respective appropriate motor axon projections. The segment-appropriate generation of spinal cord motor columns requires cooperation with other Hox proteins. Can regulate PITX3 promoter activity; may promote midbrain identity in embryonic stem cell-derived dopamine neurons by regulating PITX3. Negatively regulates the differentiation of T follicular helper cells T(FH)s. Involved in maintenance of hair follicle stem cell quiescence; the function probably involves regulation of FGF18 (By similarity). Represses transcription of various pro-apoptotic genes and cooperates with NF-kappa B-signaling in promoting B-cell expansion by inhibition of caspase-dependent apoptosis. Binds to CSF1R promoter elements and is involved in regulation of monocyte differentiation and macrophage functions; repression of CSF1R in monocytes seems to involve NCOR2 as corepressor. Involved in endothelial cell proliferation, tube formation and migration indicative for a role in angiogenesis; the role in neovascularization seems to implicate suppression of SEMA5B. Can negatively regulate androgen receptor signaling. Acts as a transcriptional activator of the FBXL7 promoter; this activity is regulated by AURKA. [Isoform 8]: Involved in transcriptional regulation in embryonic stem cells (ESCs). Stimulates expression of transcription factors that are required for pluripotency and decreases expression of differentiation-associated genes. Has distinct DNA-binding specifities as compared to the canonical form and preferentially binds DNA with the sequence 5'-CGATACAA-3' (or closely related sequences). Promotes ESC self-renewal and pluripotency (By similarity).
Synonyms: MFH; HSPC215; QRF1; 12CC4; hFKH1B
Tractability: Small molecule: it has a binding pocket of medium quality. PROTAC: UniProt records ubiquitination sites on it; ubiquitination databases record sites on it; its protein half-life has been measured.
Gene: Protein-coding gene on chromosome 3 (70,954,693 to 71,584,009, reverse strand). Ensembl gene ENSG00000114861.
Subcellular location: Nucleus
Subcellular location (Human Protein Atlas): Nucleoplasm
Pathways (Reactome):
Developmental Biology: Transcriptional regulation of pluripotent stem cells
Gene Ontology:
Molecular function: core promoter sequence-specific DNA binding; identical protein binding; nuclear androgen receptor binding; protein binding; sequence-specific double-stranded DNA binding; DNA-binding transcription factor activity, RNA polymerase II-specific; DNA-binding transcription repressor activity, RNA polymerase II-specific; RNA polymerase II cis-regulatory region sequence-specific DNA binding; DNA-binding transcription factor activity; sequence-specific DNA binding
Biological process: DNA damage response; endothelial cell activation; macrophage activation; monocyte activation; negative regulation of androgen receptor signaling pathway; negative regulation of B cell apoptotic process; negative regulation of DNA-templated transcription; negative regulation of gene expression; osteoclast development; osteoclast differentiation; positive regulation of B cell receptor signaling pathway; positive regulation of endothelial cell migration; positive regulation of smooth muscle cell proliferation; regulation of chemokine (C-X-C motif) ligand 2 production; regulation of defense response to bacterium; regulation of endothelial tube morphogenesis; regulation of gene expression; regulation of inflammatory response; regulation of interleukin-1 beta production; regulation of interleukin-12 production; regulation of macrophage colony-stimulating factor production; regulation of monocyte differentiation; regulation of tumor necrosis factor production; response to lipopolysaccharide; positive regulation of interleukin-21 production; and 12 more
Cellular component: nucleoplasm; nucleus; transcription regulator complex; chromatin
Genetic constraint (gnomAD): Loss-of-function variants: 13 observed, 74.1 expected, observed/expected ratio (o/e) 0.18, 90% interval 0.11 to 0.28. The upper end of that interval is the gene's LOEUF score, 0.28, which puts it in group 1 of 6, group 1 being the genes least tolerant of losing a copy. Missense variants: 547 observed, 745.7 expected, observed/expected ratio (o/e) 0.73, 90% interval 0.68 to 0.79. Synonymous variants: 320 observed, 279.61 expected, observed/expected ratio (o/e) 1.14, 90% interval 1.04 to 1.25.
Gene-disease validity (ClinGen):
ClinGen rates the evidence that FOXP1 causes each of these diseases.
intellectual disability-severe speech delay-mild dysmorphism syndrome (autosomal dominant): Definitive. An autosomal dominant form of syndromic intellectual disability caused by mutation in the FOXP1 gene.
congenital heart disease (autosomal dominant): Disputed. A heart disease that is present at birth.
Homologues: Orthologues: rabbit FOXP1 (98% identical), chimpanzee FOXP1 (97% identical), mouse Foxp1 (97% identical), rat Foxp1 (97% identical), pig FOXP1 (96% identical), dog FOXP1 (96% identical), macaque FOXP1 (93% identical), guinea pig FOXP1 (92% identical), tropical clawed frog foxp1 (86% identical). Paralogues in human: FOXP3 (23% identical), FOXK2 (13% identical), FOXK1 (12% identical), FOXJ3 (10% identical), FOXA2 (10% identical), FOXJ1 (10% identical), FOXA1 (10% identical), FOXD4 (10% identical), FOXI3 (10% identical), FOXD4L1 (10% identical), FOXD4L3 (10% identical), FOXD4L6 (10% identical), and 29 more.
Diseases named in the same sentence as FOXP1 in open-access papers:
FOXP1 is named in the same sentence as 274 diseases in open-access papers, as found by Europe PMC text mining. Sharing a sentence is not in itself a finding about the gene and the disease. The quoted sentences say what the papers report.
breast cancer (57 papers, 2013 to 2026). A primary or metastatic malignant neoplasm involving the breast. "For example, FOXP1 protein overexpression is associated with poor prognosis in several hematological diseases, while serving as a tumor suppressor in breast cancers; FOXP3 also indicates a better prognosis for breast cancers." (PMID 36148946, 2022). "A systematic review and meta-analysis revealed that decreased FOXP1 protein expression was significantly associated with an unfavorable relapse-free survival (RFS) in breast cancer patients." (PMID 35614183, 2022). "On the other hand, Foxp1 is located on chromosome 3p14.1, which is a tumor suppressor region; and the high expression of Foxp1 in human primary breast cancer is associated with a good prognosis, suggesting that Foxp1 is a tumor suppressor in breast cancer." (PMID 32951006, 2020). "FOXP1 deletions are found in squamous cell carcinomas of the lung, and expression of FOXP1 is associated with breast cancer development in poor prognosis in patients." (PMID 32552834, 2020). "Cytoplasmic FOXP1 predicts a poor outcome and is associated with ER and calpain II expression in breast cancer." (PMID 33006432, 2020). "In contrast, FOXP1 is also known as a tumor suppressor, since FOXP1 gene maps to a tumor suppressor locus at 3p14.1 and so loss of FOXP1 expression is associated with a poor outcome in in breast cancer." (PMID 31815635, 2019). "Overall, FOXP1 positivity, with either nuclear or an unspecified distribution, is associated with favorable survival in patients with breast cancer." (PMID 29848352, 2018). "By contrast, the loss of FOXP1 expression has been observed in human glioma, prostate cancer, and renal cell carcinoma, and the loss of FOXP1 in breast cancer is correlated with lower survival rates." (PMID 27618020, 2016). "Although a number of correlation studies have demonstrated an association between clinical outcome and FOXP1 protein expression, only a limited number of studies have been conducted to investigate the function of FOXP1 in breast cancer." (PMID 25663935, 2015). "Loss of Forkhead box P1 (FOXP1) protein expression confers a poor prognosis in sporadic and familial breast cancer patients, and the FOXP1 gene maps to a tumor suppressor locus at chromosome 3p14." (PMID 25663935, 2015). "Results of recent studies indicate that loss of FoxP1 activity promotes solid tumor proliferation, e.g. in endometrial cancer, prostate cancer, renal cell carcinoma, and breast cancer, suggesting a tumor-suppressive role in these malignancies." (PMID 25406647, 2014). "The closest correlation is the mutations in the FOX family, in which FOXA1 is somatically mutated in sporadic breast cancer and FOXP1 is germline-mutated in the BRCA1+ family." (PMID 24884718, 2014). "For instance, FOXP1 upregulation reveals a poor outcome in diffuse large B-cell lymphoma, gastric mucosa-associated lymphoid tissue lymphoma and hepatocellular carcinoma, but a good prognosis in breast cancer." (PMID 36952469, 2023). "The underlying mechanisms of the nucleocytoplasmic shuttling of FOXP1 in breast cancer are largely unknown." (PMID 29848352, 2018). "Previously, increased FOXP1 expression demonstrated a significant positive association with estrogen receptor-α (ER-α) expression in the relapse-free, borderline and overall survival of primary human breast carcinoma patients." (PMID 25663935, 2015). "Thus, loss of nuclear FOXP1 expression is correlated with a poor prognosis in breast cancer." (PMID 25663935, 2015). "Loss of FoxP1 function has been reported in several human malignancies such as endometrial cancer, lung cancer, head and neck cancer, prostate cancer, renal cell carcinoma, ovarian carcinoma, and has been shown to be associated with poor prognosis in breast cancer." (PMID 25406647, 2014). "For example, FOXP1 acts as a tumor suppressor in breast carcinoma, lung cancer, and prostate cancer." (PMID 40672953, 2025).
breast cancer (continued). "FOXP1 is identified as a negative regulator of immune responses by regulating expression of cytokine and chemokine in breast cancer, which is consistent with the results obtained from our enrichment analysis." (PMID 38652109, 2024). "In breast cancer, the expression of FOXP1 is positively correlated with the infiltration of CD4 + T cells, CD8 + T cells, neutrophils and macrophages, but different from our findings, the expression of FOXP1 is negatively correlated with B cells." (PMID 38652109, 2024). "The expressed FOXP1 protein promoted breast cancer cell proliferation by activating oestrogen receptor (ER) signalling." (PMID 37795443, 2023). "In contrary, FOXP1 worked also as a tumor suppressor with good prognosis in breast cancer and lung carcinoma." (PMID 36952469, 2023). "In a cross-sectional study of breast cancer, an analysis of stage I to III breast cancer patients who received NAC from 2018 to 2019 found that, in response to treatment, there was a significant association between complete response and FOXP1 (p = 0.01)." (PMID 38087296, 2023). "In this study, database analysis showed that the transcription levels of FOXP1 in human breast cancer were lower than in normal tissues, and immunohistochemical staining from our breast carcinoma specimen also demonstrated this result." (PMID 35614183, 2022). "Deletion of Foxp1 increased mammary tumour latency and slightly decreased metastasis compared to the wild type (WT)." (PMID 33751828, 2021). "Knockdown of FOXP1 decreased gene expression of Gata3 and Esr1, along with diminishing ERα protein expression in WT mouse mammary epithelial cells as well as in human breast cancer cells, MCF7." (PMID 32934200, 2020). "FOXP1 expression is also positively correlated with hormone receptor status and breast cancer sensitivity to endocrine therapy." (PMID 32934200, 2020). "This is exemplified by the activation of FOXP1 transcription in breast cancer stem cells and DVL3 transcription, an activator of Wnt/β-catenin, in CML-LSCs (leukemic stem cells), which were linked with PRMT5 activity." (PMID 32743345, 2020). "FOXP1 is a transcription factor essential for the development of major organs and known to be a tumor suppressor in prostrate and breast cancers." (PMID 32577159, 2020). "A study shows that FOXP1 is a key factor in PRMT5-induced breast cancer stem cells and PRMT5 can be recruited to the FOXP1 promoter to facilitates recruitment of H3R2me2s, SET1 and H3K4me3." (PMID 32859239, 2020). "FOXP1 regulates cell viability in breast cancer by acting as an estrogen‐inducible transcription factor." (PMID 33006432, 2020). "PRMT5 epigenetically upregulates Forkhead box protein P1 (FOXP1) expression through histone H3 methylation (H3R2me2s) at this gene promotor for breast cancer stem cells’ maintenance." (PMID 32859041, 2020). "FOXP1 has protein-protein interaction with NFAT1 to enhance breast cancer cell motility and FOXP2 is essential in growth arrest of 143 osteosarcoma cells via p21 activation." (PMID 31815635, 2019). "Foxp1 is highly expressed in oestrogen receptor-positive human breast cancer cells and can inhibit the migration of tumour-infiltrating T cells." (PMID 31594465, 2019). "It has been shown that FoxP1 expression is regulated by PI3K/AKT/p70S6K signaling cascade in breast cancer." (PMID 31305241, 2019). "FOXP1 also enhanced the migration of MDA-MB-231 metastatic breast cancer cells via transcriptional repressing of NFAT152." (PMID 30057418, 2018). "The PI3K/AKT/p70S6K signaling pathway, which has been reported to be involved in the nucleus-cytoplasm shuttling of FOXO1, another forkhead protein family member, was previously shown to participate in FOXP1 regulation in breast cancer." (PMID 29848352, 2018).
breast cancer (continued). "The evidence presented in the current study indicated a negative regulation of HDAC4 and FOXP1 by miR-22 in fulvestrant-resistant breast cancer cells, which supports previous reports showing that HDAC4 and FOXP1 were direct targets of miR-2249,50." (PMID 30057418, 2018). "Here we describe our recent findings that PRMT5 is a critical regulator of breast cancer stem cell survival via the epigenetic regulation of FOXP1." (PMID 29876520, 2018). "To date, we are not aware of any literature establishing the relevance between calpain II and FOXP1 protein in breast cancer." (PMID 29848352, 2018). "Further investigations are needed to better understand the biological role of FOXP1 expression in breast cancer development and progression and to provide better strategies for prognosis prediction and therapeutic intervention in breast cancer." (PMID 29848352, 2018). "In contrast, our findings clearly show that FOXP1 is pro-oncogenic, promoting breast cancer cell proliferation and in vivo tumor growth." (PMID 29262329, 2017). "Clinically, we find that combined FOXP1 and PTEN loss in human prostate, breast cancer, and head and neck cancer correlates with increased cancer recurrence, suggesting that combined deletion has functional and prognostic significance in cancer." (PMID 29057879, 2017). "To date, immunohistochemical analysis has suggested that FOXP1 functions as a breast cancer tumor suppressor gene, as low levels correlate with poor prognosis." (PMID 29262329, 2017). "show that the arginine methyltransferase PRMT5 contributes to breast cancer stem cell function, in part through histone methylation regulating FOXP1 expression." (PMID 29262329, 2017). "In contrast, FOXP1 was reported to act as a potential tumor suppressor in prostate cancer, renal cell carcinoma, or breast cancer." (PMID 26654944, 2016). "In estrogen receptor α-positive MCF-7 breast cancer cells, overexpression of FOXP1 by exogenous transfection increased cell proliferation whereas knockdown of FOXP1 expression by siRNA decreased proliferation of MCF-7 cells." (PMID 26654944, 2016). "It has previously been identified that FOXP1 is regulated by estrogen in breast cancer and that treatment with bisphenol A is effective for regulating the transformation of the normal human breast epithelial cell line, MCF-10F." (PMID 25663935, 2015). "In tumors such as diffuse large B-cell lymphoma, glioblastoma and hepatocellular carcinoma, FOXP1 exhibits oncogenic functions, however, in breast cancer, FOXP1 has been detected to act as a tumor suppressor." (PMID 25663935, 2015). "For example, strong nuclear staining and/or heterogeneous weak nuclear staining of FOXP1 were identified in different stages of breast cancer progression." (PMID 25663935, 2015). "Although correlation studies have indicated that FOXP1 has a role in tumor suppression, determination of the regulatory mechanism of FOXP1 is required to establish its function in breast cancer." (PMID 25663935, 2015). "However, in the metastatic melanoma and breast cancer cohorts that underwent immunotherapy, patients with low FOXP1 expression demonstrated a significantly higher therapy response compared to those with high FOXP1 expression." (PMID 40672953, 2025). "Survival analysis results showed that increased FOXP1 mRNA levels were significantly associated with overall survival (OS), recurrence-free survival (RFS), and distant metastasis-free survival (DMFS) in all patients with breast cancer (P < .05)." (PMID 38608123, 2024). "In contrast, calpain-2 played an important role in the nucleocytoplasmic trafficking of forkhead box protein P1 (FOXP1) via the PI3K-AKT pathway in breast cancer patients; cytoplasmic relocalization of FOXP1 correlated with reduced overall survival in breast invasive ductal carcinoma patients." (PMID 37795261, 2023). "Forkhead-box-P family include FOXP1/2/3/4 and its clinical significance still remains unclear in breast cancer (BRCA)." (PMID 35614183, 2022).